EGFR (epidermal growth factor receptor)
Diseases named in the same sentence as EGFR in open-access papers (continued):
Sharing a sentence is not in itself a finding about the gene and the disease.
anemia (30 papers, 2009 to 2025). A reduction in the number of red blood cells, the amount of hemoglobin, and/or the volume of packed red blood cells. "These included smoking history, performance status, weight loss, anemia, elevated lactate dehydrogenase levels, response to prior chemotherapy, time from diagnosis, number of prior treatment regimens, EGFR copy number, and ethnicity." (PMID 40805260, 2025). "One gene EGFR was found to have functional association with ID anemia, suggesting potential for using E. sativa extracts." (PMID 39479620, 2024). "Multivariate analyses identified baseline anemia as a factor predicting a poor prognosis in terms of OS in patients with EGFR mutations." (PMID 36253772, 2022). "In this study, we focused on the relationship between baseline anemia and prognosis in patients with EGFR-mutated NSCLC treated with targeted therapy." (PMID 36253772, 2022). "Baseline anemia was significantly correlated with prognosis in these patients, with OS decreasing in line with increasing anemia grade in patients with EGFR mutations treated with targeted therapy." (PMID 36253772, 2022). "We therefore conducted a retrospective study of 2,029 patients with stage IV EGFR-mutated NSCLC who received EGFR-TKI therapy to investigate the prognostic value of baseline anemia and anemia grade in these patients." (PMID 36253772, 2022). "The present analysis identified baseline anemia as a factor associated with a poor prognosis in patients with NSCLC with EGFR mutations." (PMID 36253772, 2022). "With regard to the risk of grade 3–4 diarrhea, nausea, vomiting, and anemia, equivalent frequencies were found between the EGFR-TKI arm and the chemotherapy arm." (PMID 25029199, 2014). "This represents the largest study of the importance of anemia in EGFR-mutated NSCLC." (PMID 36253772, 2022). "A total of 2,029 patients treated with EGFR-tyrosine kinase inhibitors (TKIs) were finally enrolled in this study, of whom 24.6% had baseline anemia." (PMID 36253772, 2022). "Baseline anemia is a significant factor predicting a poor prognosis in terms of OS in patients with NSCLC and EGFR mutations treated with targeted therapy." (PMID 36253772, 2022). "The most common AEs in the EGFR-WT cohort were anemia (92.3%) and vomiting (25.0%), whereas those in the EGFR-mutant cohort were rash (60.0%), anemia (53.0%), and diarrhea (20%)." (PMID 36076157, 2022). "The risk of grade 1–5 vomiting, nausea, neutropenia, leucopenia, platelet count decrease, anaemia and fatigue significantly increased in control group when compared with adjuvant EGFR-TKIs." (PMID 35346117, 2022). "This study demonstrated that baseline anemia and anemia grade were significantly correlated with prognosis in patients with NSCLC with EGFR mutations who received targeted therapy." (PMID 36253772, 2022). "We retrospectively analyzed anemia‐related data for patients with NSCLC and EGFR mutations who were admitted to Zhejiang Cancer Hospital from January 2013 to June 2019 and treated with targeted therapy." (PMID 36253772, 2022). "For 1G EGFR-TKIs with chemotherapy, neutropenia, anemia, and thrombocytopenia were more common, the rates of grade 3 for these hematological toxicities were 33.3% (n = 2), 25.0% (n = 3), and 16.7% (n = 2)." (PMID 36188595, 2022). "For any grade of AEs, the incidence of nausea, anemia, constipation, vomiting, decreased appetite, and fatigue in the Osimertinib therapy subgroup was significantly lower than in the EGFR-TKIs/chemotherapy subgroup." (PMID 31651902, 2019). "Regarding the incidence of adverse events, compared with the EGFR-TKIs or chemotherapy alone group, the combination group showed a higher incidence of grade 3–4 leucopoenia, neutropenia, febrile neutropenia, anaemia, rash, fatigue and diarrhoea." (PMID 27223081, 2016).
anemia (continued). "Gefitinib, an epidermal growth factor receptor-tyrosine kinase inhibitor (EGFR-TKI), can also induce erythrocyte shrinkage and cell membrane phospholipid scrambling, and combination of EGFR-TKI and chemotherapy is associated with an even higher incidence of all-grade anemia." (PMID 37208766, 2023). "The most common AEs in the EGFR-WT cohort were anemia (92.3%) and vomiting (25.0%)." (PMID 36076157, 2022). "All patients developed iron deficiency and one severe anemia which has also not been described previously for the use of EGFR inhibitors." (PMID 24795806, 2013). "Compared with EGFR TKIs and monotherapy, the patients who received synchronous combination therapy presented with a significant increase in the incidence of grade 3/4 anemia and fatigue (anemia: RR = 6.71, 95%CI = 1.25–35.93, P = 0.026; fatigue: RR = 9.60, 95%CI = 2.28–40.86, P = 0.002)." (PMID 26285137, 2015). "The occurrence rates of anemia for VEGF and EGFR inhibitors were 26% (95% CI: 7%, 44%) and 42% (95% CI: 3%, 87%)." (PMID 37324019, 2023). "However, as the largest study of anemia in patients with NSCLC with EGFR mutations, we believe that the results are of great significance and may help to guide the treatment of NSCLC in patients with EGFR mutations." (PMID 36253772, 2022). "In addition, PS 0/1/2 (P=0.0002), stage IIIB disease (P=0.0011), a history of EGFR-TKI treatment (P=0.0007), female gender (P=0.0320), grade 3 or 4 neutropenia (P=0.0002) and grade 0 anemia (P<0.0001) were also independent favorable prognostic factors." (PMID 23426938, 2013).
cyst (29 papers, 2012 to 2025). A sac-like closed membranous structure that may be empty or contain fluid or amorphous material. "This study highlights a bidirectional feedback mechanism that underlies cyst cell-germline reciprocal communication that controls the signaling strength among EGFR, JNK, p38, and ROS within the Drosophila testis cysts." (PMID 41106385, 2025). "Notch is activated in almost all SGPs and is required to specify hub cell identity, whereas in posterior SGPs, hub cell fate is repressed by activation of EGFR, causing these cells to differentiate into cyst lineage cells instead." (PMID 35468055, 2022). "We conclude that activation of EGFR signaling in adult hub cells is sufficient to cause their conversion to cyst lineage cells." (PMID 35468055, 2022). "The ectopic activation of EGFR signaling in cyst cells ultimately contributes to the loss of GSCs and early spermatogonia due to differentiation." (PMID 31873089, 2019). "Together, these analyses suggested that the loss of EGFR activity disrupts the synchrony of germline divisions within a cyst during TA (4–16 cell stages)." (PMID 30045884, 2018). "Further, we found that the cyst enclosure was intact in several over-proliferated cysts in the EGFR loss-of-function backgrounds." (PMID 30045884, 2018). "A prior study indicated that HB-EGF leads to proliferation and is the most important ligand of the EGFR that might contribute to cyst growth due to its increased excretion associated with ADPKD disease severity." (PMID 36914219, 2023). "We propose a model where, after CySC ablation, hub cell proliferation and conversion to CySCs are driven by EGFR signaling, promoted by a new signal (EGF ligands from germ cells) not normally received by the hub, and by loss of an existing signal (the EGFR inhibitor Argos from cyst lineage cells)." (PMID 35468055, 2022). "Furthermore, pharmacological inhibition with EGFR-specific tyrosine kinase inhibitors caused a decreased EGFR activity leading to a significant reduction of cyst progression." (PMID 34204582, 2021). "In the Drosophila testis, a pair of somatic cyst cells (CCs) encapsulate the germline that differentiates through close-range EGFR signaling activation." (PMID 41106385, 2025). "In vitro and in vivo experiments have demonstrated that activation of the EGFR pathway leads to cyst development, whereas pharmacological targeting of the EGFR pathway resulted in reduced kidney growth in animals models." (PMID 36914219, 2023). "In the ADPKD slices, phosphorylated EGFR was present at cyst lining epithelial cells of most cysts at the apical cell membrane, whereas phosphorylated ErbB2 was absent and phosphorylated ErbB4 was only present in some cysts (not shown)." (PMID 36914219, 2023). "Here, we show that activation of the EGFR signaling pathway in the hub is sufficient to drive hub cell proliferation and conversion to cyst lineage cells in adult testes." (PMID 35468055, 2022). "We propose that EGFR signaling, which is normally required in adult cyst cells, is actively inhibited in adult hub cells to maintain their fate but is repurposed to drive stem cell regeneration after CySC ablation." (PMID 35468055, 2022). "In the developing Drosophila testis, the EGFR signaling pathway is essential for the formation and function of cyst cells." (PMID 35468055, 2022). "In adult testes, EGFR signaling is required in cyst lineage cells for their encapsulation of germ cells, and this association is vital for germ cell differentiation and maturation into sperm." (PMID 35468055, 2022). "Higher levels of EGFR activation in cyst cells are required for spermatogonia to end the TA divisions and initiate the spermatocyte pre-meiotic program." (PMID 35563080, 2022). "In adult testes, the EGF ligand Spitz is known to be secreted from germ cells and received by cyst cells, where activation of the EGFR pathway is essential for their proper encystment of the germ cells." (PMID 35468055, 2022).
cyst (continued). "EGFR inhibitors, such as EKI-785, EKB-569, and Tesevatinib, and the Src inhibitor SKI-606, which also inhibits the EGFR signaling, have been shown to slow cyst growth in rodent models of ARPKD, ADPKD, and other forms of PKD." (PMID 34650051, 2021). "The binding of nimotuzumab to EGFR in the renal cysts was implemented in the peripheral compartment, since EGFR is localized at the basolateral membrane in renal tubular cells and at both apical and basolateral membranes of cyst epithelial cells." (PMID 33256255, 2020). "The mean immunohistochemical positive cell percentage of EGFR had a positive correlation with the cyst volume (r = 0.782, p < 0.01)." (PMID 32432044, 2020). "Immunohistochemistry analysis revealed that the patients' cyst volume was related to the upregulation of EGFR (r = 0.532, p = 0.023)." (PMID 32432044, 2020). "This is in line with results showing that the TGFα and EGFR autocrine loops provide a platform for renal-cyst formation." (PMID 32432044, 2020). "Several studies suggest that EGFR, ErbB2 and their ligands enhance the proliferation of tubular epithelial cell, leading to cyst formation." (PMID 33256255, 2020). "Overexpression of EGFR was present in a variety of VHL mutations, and the volume of the cyst was related to the upregulation of EGFR (r = 0.532; p = 0.023)." (PMID 32432044, 2020). "Di-phosphorylation of ERK (dpERK) in somatic cyst cells can be used as a read-out of EGFR signaling and measured to assess levels of EGFR activation." (PMID 31873089, 2019). "Mitochondrially-derived ROS can influence early spermatogonia to differentiate through the activation of the EGFR pathway in their neighboring somatic cyst cells." (PMID 31873089, 2019). "Inhibition of Drp1 in early germ cells resulted in the loss of GSCs and spermatogonia due to the accumulation of reactive oxygen species (ROS) and activation of the EGFR pathway in adjacent somatic cyst cells." (PMID 31873089, 2019). "It is established that EGFR/MAPK signaling is required in the somatic cyst cells for their proper differentiation and engulfment of the developing germline cells." (PMID 30992503, 2019). "Germ cells express and secrete the EGF-ligand Spitz, which binds to the EGFR and activates signaling in cyst cells." (PMID 31873089, 2019). "Recently, it was demonstrated that elevated ROS in germ cells can contribute to the activation of the EGFR signaling pathway in somatic cyst cells." (PMID 31873089, 2019). "Although the exact mechanism is unclear, the epidermal growth factor receptor (EGFR) activation in SCCs has been reported to control spermatogonial divisions within a cyst, through downstream activations of Rac1-dependent pathways." (PMID 30045884, 2018). "EGFR-dependent Rac1 activation in SCCs is suggested to play an essential role in controlling the germline proliferation and differentiation within a cyst." (PMID 30045884, 2018). "Collectively, HDAC6 contributes to cyst growth by promoting cell proliferation and fluid secretion induced by aberrant Ca2+ signalling, abnormal cAMP signalling, and prolonged EGFR signalling." (PMID 30134806, 2018). "The results suggest that Rolled/ERK-MAPK activation in SCCs downstream of EGFR is essential for synchronizing the germ-cell divisions within a cyst at every step during the TA." (PMID 30045884, 2018). "Altogether, these results indicated that EGFR–ERK activation in SCCs is required at every TA-division cycle to synchronize the germ-cell divisions within a cyst." (PMID 30045884, 2018). "This cSrc-mediated activation of STAT 3 is augmented by increased activity of the EGFR axis and increased cAMP, thereby promoting even greater proliferation of tubular epithelium and cyst enlargement." (PMID 28473970, 2017). "Although erlotinib has not previously been assessed, some prior studies have used alternative inhibitors of EGFR or related ERBB-family kinases in various models for cyst formation." (PMID 26528438, 2015).
cyst (continued). "In the current study, to probe these novel actions of AURKA in ADPKD, we have evaluated the interaction of the EGFR inhibitor erlotinib with alisertib in control of cyst formation." (PMID 26528438, 2015). "Elevated levels of PD-L1 have been identified in ACP cyst cavity linings which correlates with Epidermal Growth Factor Receptor (EGFR) activation in ACP, providing rationale for the use of immune checkpoint inhibitors (ICI) through effects on EGFR and MAPK/ERK pathways inhibiting tumor growth." (PMID 37886179, 2023). "While Notch is expressed in all somatic gonadal precursor cells (SGPs) and required for hub cell fate during embryogenesis, EGFR signaling is only expressed in a subset, repressing hub cell fate and enabling these cells to differentiate into cyst lineage cells." (PMID 35468055, 2022). "Evidence showed that the stet gene, whose encoded protein could catalyze proteolytic cleavage of spi within the Golgi, was required for male fertility and encapsulation of germ cells to promote differentiation via EGFR signaling on somatic cyst cells." (PMID 33990549, 2021). "This suggests that the capacity of EGFR inhibition at the cyst level (peripheral compartment) may be much higher than observed in central compartment, and the peripheral compartment is responsible for most of the nonlinearity seen in nimotuzumab PK." (PMID 33256255, 2020). "The somatic activation of the novel EGFR-ERK pathway synchronizes germline mitoses within a cyst." (PMID 30045884, 2018). "Since our findings showed that UROtsa cyst formations were decreased by blocking EGFr, we wanted to explore whether tight junction proteins were affected by EGFr blockade." (PMID 29508172, 2018). "Furthermore, studying expression changes in EGFR gene in frozen and warmed blasto-cyst embryos demonstrated a 1.54 fold increase compared with control blastocyst embryos without freezing and warming." (PMID 29849990, 2018). "We suspected that upregulated HDAC6 might also contribute to the mislocalization of the apical EGFR on cyst lining epithelia." (PMID 23152903, 2012). "Given these considerations, we investigated in the present study whether EGFR pathway activation is associated with disease progression during follow-up in a cohort of ADPKD patients, and whether such an association reflects a role in cyst growth or repair." (PMID 36914219, 2023). "Our results support the hypothesis that EGFR signaling, which normally functions in cyst cells and germ cells in adult testes, is repurposed after complete CySC ablation to drive the de novo formation of stem cells from adjacent quiescent niche cells in an adult tissue." (PMID 35468055, 2022). "However, Argos is induced by EGFR signaling, which occurs at high levels in cyst lineage cells in adult testes, suggesting that cyst lineage cells could be a source of Argos in the testis." (PMID 35468055, 2022). "Moreover, SBH could also repress the phosphorylation of EGFR in cyst-lining epithelial cells stimulated by EGF." (PMID 33986666, 2021). "Therefore, SBH may inhibit PKD cyst growth by inhibiting phosphorylation of EGFR and decreasing the proliferation of the cyst-lining epithelial cells." (PMID 33986666, 2021). "Finally, the cyst volume was related to the upregulation of EGFR (r = 0.782, p < 0.01)." (PMID 32432044, 2020). "Therefore, the occurrence of irregular-size cysts observed in the EGFR and ERK loss-of-function backgrounds could arise due to the asynchronous division of germline cells within a cyst." (PMID 30045884, 2018). "HDAC6 has been recognized to exacerbate cyst growth in ADPKD through enhancing cAMP signaling and upregulating epidermal growth factor receptor (EGFR) activity." (PMID 37152951, 2023). "The first evidence that the epidermal growth factor receptor (EGFR) axis was altered in PKD was in 1992, by demonstrating that cells from primary cultures of PKD patients increased cyst expansion." (PMID 34204582, 2021).